MTOR (mechanistic target of rapamycin kinase)
Diseases named in the same sentence as MTOR in open-access papers (continued):
Sharing a sentence is not in itself a finding about the gene and the disease.
tumor (continued). "Activated AKT can participate in multiple signaling pathways and regulate transcription and protein synthesis via activating the downstream mTOR directly or through some cytokines to play an important role in the growth and proliferation of tumor cells." (PMID 31762993, 2019). "In view of the efficacy and safety associated with tumor and seizure frequency in the TSC patients, mTOR inhibitors is a good therapeutic choice." (PMID 30760308, 2019). "The phosphoinositide 3-kinase (PI3K)/mammalian target of rapamycin (mTOR) signaling pathway is found to be activated in the tumor cells." (PMID 31654067, 2019). "The PI3K/Akt/mTOR axis is a known crucial signaling pathway for cell growth, survival and metabolism in tumor cells." (PMID 30849993, 2019). "This tumor-suppressing effect induced by either local or systemic administration of Sema3F was attributed to Sema3F/NRP2-mediated inhibition of Akt-mTOR signaling." (PMID 31052281, 2019). "EGFR-TKI induces autophagy through the suppression of the PI3K/AKT/mTOR signaling pathway, which in turn saves tumor cells from the harm of EGFR-TKIs." (PMID 31811814, 2019). "The phosphoinositide-3-kinase (PI3K)/AKT/mTOR pathway is active in diverse tumor entities, such as breast cancer, colon cancer, and cholangiocarcinoma." (PMID 31277283, 2019). "The inhibition of mTOR increases immunosurveillance, modulating the interactions between the tumor microenvironment and tumor cells." (PMID 31766386, 2019). "Immunoblot analysis of Akt/mTOR pathway members in tumor lysates confirmed on-target effects for both sirolimus and AZD8055 at 6 h after treatment." (PMID 31519159, 2019). "Activation of the AKT/mTOR pathway leads to therapeutic resistance and is a poor prognostic factor in many tumours, which mainly relies on the binding of ligands to receptors in the cell membrane." (PMID 31139014, 2019). "In this signaling network, an increased level of AMP activates AMPK, which inhibits the mammalian target of rapamycin (mTOR) expression to reduce tumor progression." (PMID 30754684, 2019). "In renal tumor cells, VPS34 inhibition by SAR405, a highly potent and selective kinase inhibitor, resulted in tumor cell death under starvation or combined with mTOR inhibition." (PMID 31515514, 2019). "More interestingly, low dose of ALM treatment enhanced the anti-tumor effect of Everolimus, an inhibitor of mTOR, suggesting its potential use in combination therapy of tumors, especially solid tumor patients." (PMID 31083403, 2019). "AMPK affects cell growth via mammalian target of rapamycin (mTOR), thereby inhibiting the induction of tumor formation." (PMID 31121868, 2019). "Immunohistochemical staining of tumor tissue showed that the area positive for p-Akt and p-mTOR was smaller in the Rk3 group than in the control group." (PMID 31091245, 2019). "This study showed that inhibiting CCL5-CCR5 signaling in endothelial cells led to protein kinase B (AKT)/mTOR pathway activation defects as well as vascular and tumor growth defects in vitro and in vivo." (PMID 31500658, 2019). "Mechanistically, TRIP13 interacted with ACTN4 and positively regulated its expression, thus activating the AKT/mTOR pathway to drive tumor progression." (PMID 31533816, 2019). "A randomized trial focused on patients with mTOR over-expression within the tumour is required to strengthen the evidence and to advance towards a true personalized immunosuppression in HCC." (PMID 30650598, 2019). "Again, the downregulation of Notch1, which occurs as a downstream effect of PrPc silencing, inhibits the PI3K/Akt/mTOR pathway to abolish GSCs’ stemness, self-renewal, invasiveness and in vivo tumor growth." (PMID 31618844, 2019). "Overall, our data clearly and originally demonstrate the benefit of using drug combinations such as irinotecan and catalytic mTOR inhibitors to prevent tumor progression and/or the dissemination process." (PMID 31627299, 2019).
tumor (continued). "While the most validated anti-oncogenic duty of PTEN is the negative regulation of the PI3K/mTOR/Akt oncogenic signaling pathway, further tumor suppressor functions, such as chromosomal integrity and DNA repair have been reported." (PMID 31404976, 2019). "It is known that mTOR inhibitors such as rapamycin or everolimus have anti-epileptogenic effects rather than a simple seizure-suppression effect, as well as anti-tumor effects in TS." (PMID 31875159, 2019). "The down-regulation of these pathways would reduce angiogenesis, inflammation, and mTOR signaling, while enhancing tumour cell apoptosis." (PMID 31149644, 2019). "Kim found ELH can attenuate HIF-1α accumulation by blocking phosphorylation of AKT/mTOR/p70S6K to inhibit tumor angiogenesis." (PMID 31022939, 2019). "Despite some loopholes, further attention should be given to the understanding of the mTOR signaling pathway and its downstream processing which play a vital role in tumor progression." (PMID 31030499, 2019). "The purpose of this study was to investigate the potential of inhibiting mTOR to modulate DC functions for elevating the anti-tumor effects of DNA vaccines." (PMID 31052575, 2019). "Dual treatment of eribulin and the mTOR inhibitor results in a synergistic suppression of cell survival in a number of TNBCs in vitro and an enhanced suppression of tumor growth in two TNBC mouse models." (PMID 31480338, 2019). "Tumor cells from these mice demonstrated high activity of the AKT/ mammalian target of rapamycin (mTOR) and Ras/ Mitogen-activated protein kinase (MAPK) signaling cascades, two pathways frequently co-induced in human HCC." (PMID 31277283, 2019). "Among the most promising pharmacological agents targeting downstream signaling mediators shared by both IGF-IR and RTKs, the combination of anti-mTOR compounds with different kinase inhibitors has generated encouraging reductions in tumor growth." (PMID 31269742, 2019). "Based on these results, we next determined the effect of the mTOR inhibitor AZD2014 alone or in combination with irinotecan on tumor growth in vivo." (PMID 31627299, 2019). "Emerging lines of evidence link metabolic alterations and mTOR aberrant activation with sustained pro-tumorigenic activities of the HIPPO tumor suppressor pathway." (PMID 31399037, 2019). "To determine if the signaling pathways observed in our animal model are present in human HCC we investigated the expression of the mTOR and Src pathways in human tumor tissues (Westmead Liver Clinic)." (PMID 30794695, 2019). "The mTOR inhibitors Rapamycin and RAD001 reduced tumour burden in HPV-positive HNSCC xenografts through the inhibition of mTOR activity." (PMID 30970654, 2019). "Various studies have demonstrated the efficacy of mTOR pathway inhibition on reducing tumor growth and specifically inhibiting proliferation of CSCs." (PMID 31191243, 2019). "More importantly, we discovered for the first time that CASC9 regulates autophagy through the AKT/mTOR pathway in tumor cells, promoting autophagy-mediated apoptosis." (PMID 30674868, 2019). "For instance, NVP-BEZ235, a dual inhibitor of PI3K and mTOR signaling, inhibited tumor growth in a genetically engineered mouse model of sporadic CRC." (PMID 30754640, 2019). "Given that the tumor suppressor PTEN counteracts the mTOR pathway, downstream targets of mTOR were analyzed for phosphorylation." (PMID 31114481, 2019). "mTOR is reported to govern M-MDSCs in mouse allograft and tumor models, and glycolysis via mTOR activation is essential for M-MDSCs to differentiate and acquire immunosuppressive ability." (PMID 31011190, 2019).
tumor (continued). "Knockdown SNRPE significantly reduces the expressed level of mTOR mRNA and protein, and is accompanied by the imbalance of the mTOR pathway, which activates abnormal mTOR signaling and which can result in the growth and metastasis of tumor cells." (PMID 30881302, 2019). "Rapamycin and everolimus bind to FKBP12 (FK 506-binding protein of 12 kDa) to prevent mTOR from activating mTORC1 abnormally and then control cellular proliferation to stop benign tumor growth." (PMID 30760308, 2019). "Sensitivity to Akt-specific inhibitors is dependent upon activation of the PI3K/Akt/mTOR pathway in tumor cells." (PMID 30943918, 2019). "Kindlin-2 also facilitates VEGFA-dependent angiogenesis and tumour progression through the mTOR pathway." (PMID 31427543, 2019). "Here, the authors present a case report of a patient with kidney allograft and show that treatment with the mTOR inhibitor sirolimus preserves peripheral tolerance and anti-tumour efficacy of ICI therapy." (PMID 31624262, 2019). "Our results also indicate that CTC abrogated the mTOR activation at Ser residue 2448 in tumor cells." (PMID 30813295, 2019). "mTOR inhibitors have shown promising anti-tumor activity in preclinical studies and early stage clinical trials in HNSCC." (PMID 31905951, 2019). "The patient with 100% p-mTOR staining was a 42-year-old woman with stage 1a disease, 12 cm tumor size, 2/10 HPF mitoses, and low-grade atypia." (PMID 30592193, 2019). "ROS are able to activate the PI3K/AKT/mTOR pathway and mediate the proliferation and migration of tumor cells." (PMID 31636809, 2019). "These authors reported a mechanism by which tumor cells can quickly adapt to radiation-induced DNA damage via mTOR-mediated reprogramming of bioenergetics from predominantly aerobic glycolysis to mitochondrial oxidative phosphorylation." (PMID 31395939, 2019). "Any protein in the PI3K/AKT/mTOR pathway can be targeted for the clinical inhibition of mTOR activation in tumor tissues." (PMID 31929797, 2019). "Here, we have shown that EZH2 inhibition induced is able to eliminate LMS stem-like cells and to restore the anti-tumor effect of dual PI3K/mTOR inhibition in vitro and in vivo." (PMID 30683135, 2019). "The repression of EGFR/VEGFR- and mTOR-related pathways in concert seemingly reverts processes predominantly responsible for uncontrolled TNBC tumor proliferation." (PMID 31388935, 2019). "Partially consistent with these observations are the results reported by a study showing that stimulation of stress-induced autophagy obtained through mTOR inhibition improves muscle phenotype in tumor hosts." (PMID 30833900, 2019). "The phosphatidylinositol 3-kinase(P3K)/AKT pathway is the mammalian target of rapamycin (mTOR) pathway, a key regulator of growth, angiogenesis, and tumor cell survival." (PMID 31151284, 2019). "In a preliminary retrospective analysis of 7 patients treated with the MTOR inhibitor everolimus a decrease in tumor markers was noted in 5 patients." (PMID 30713600, 2019). "We found that coordinated autophagy and mTOR inhibition enhanced cell death and induced tumor remission only in HIF-2α-silenced cells." (PMID 31151160, 2019). "We suggest that elevated kindlin-2 promotes VEGFA-dependent angiogenesis and tumour progression via the mTOR pathway." (PMID 31427543, 2019). "Following molecular analysis of tumor tissue samples, patients with phosphorylated mTOR-Ser2448 will receive temsirolimus in addition to standard radiotherapy." (PMID 31510109, 2019). "In a nude mouse xenograft tumor model, stable knock down of PKM2 in PC3 cells (a human prostate cancer cell line with PTEN deficiency and mTOR hyperactivation) significantly extended the survival of tumor-bearing mice." (PMID 30857125, 2019). "Activation of the PI3K/AKT/mTOR pathway contributes to the development of tumor and resistance to anticancer therapies." (PMID 30782187, 2019).
tumor (continued). "We found that B7-H3 regulates OSCC glucose metabolism through the PI3K/Akt/mTOR pathway, which contributes to enhanced tumor cell proliferation, migration and invasion." (PMID 31737114, 2019). "As an example, the PI3K-Akt-mTOR signaling is poised toward activation in mice implanted with the C26 tumor, while protein synthesis rates are unchanged with respect to controls in rats hosting the Yoshida AH-130 hepatoma or the MCA sarcoma." (PMID 30833900, 2019). "Tumor cells and osteogenic cells form heterotypic adherent junctions, which improve mTOR activity and guide bone colonization." (PMID 31766386, 2019). "Several mTOR/P13K (turquoise dots) and the cSrc inhibitor Dasatinib (green dot) showed anti-tumour activity in K-SS3." (PMID 30745580, 2019). "Previous studies have shown that kisspeptin signaling through GPR54 inhibits phosphatidylinositol-3-kinase (PI3K)/Akt pathway, negatively regulating mTOR signaling, in tumor cells." (PMID 31767891, 2019). "Tuberous sclerosis complex (TSC) 1 and 2 function as tumor suppressors by inactivating the mammalian target of rapamycin (mTOR) pathway." (PMID 30842342, 2019). "Several studies proposed that inhibition of PI3K/Akt/mTOR pathway increased autophagy and effectively reduced the tumor outgrowth." (PMID 30881282, 2019). "At the molecular level, tumor cell adaptation to hypoxia is regulated in part by the PI3K/AKT/mTOR pathway and by the transcription factors HIF-1α and HIF-2α, whose protein expression and transcriptional activity are also partly regulated by mTOR." (PMID 31627299, 2019). "The anti-tumor chemical E Platinum induces autophagy in various carcinoma cell lines by decreasing phosphorylation of p38 and inhibiting mTOR activation." (PMID 31547619, 2019). "CircNRIP1 can alter metabolism and autophagy through the AKT1/mTOR axis and promote tumour metastasis through exosome communication." (PMID 30717751, 2019). "Among them, AZD8055 inhibits both mTOR complexes and has shown to inhibit tumor growth and induce ACD in hepatocellular carcinoma cell lines, but it is also capable of limiting tumor growth through induction of apoptosis and cell cycle arrest." (PMID 31635099, 2019). "Recent studies have revealed that berberine has anti-tumor effects, through inhibition of the mTOR-signaling pathway." (PMID 30987378, 2019). "Activation of the AKT/mTOR and RAS/MAPK cascades is frequently observed and associated with aggressive tumor phenotypes and poor prognosis in human HCC." (PMID 31619257, 2019). "In a different fashion, rapalogs that inhibit mTOR (e.g., rapamycin and its derivatives, everolimus, and temsirolimus) exhibit anti-tumor effects by targeting PI3K/Akt/mTOR axis and cell proliferation." (PMID 31921661, 2019). "It is well known that increased ROS production in tumor cells induces the uncontrolled activation of the PI3K signaling pathway (PI3K/Akt/mTOR), in comparison with the response of normal cells." (PMID 31505728, 2019). "Separate from its classical role in detoxification of ROS, NRF2 can also influence PI3K signaling, and has been shown to activate transcription of the gene coding for mechanistic Target of Rapamycin (mTOR), a common promoter of tumor growth." (PMID 31398789, 2019). "Targeting PI3K/AKT/mTOR signaling can not only induce apoptosis to inhibit the proliferation of tumor cells, but also induce autophagy." (PMID 31871431, 2019). "In approximately 88% of patients with GBM, spontaneous upregulation of the PI3K/Akt/mTOR pathway activates growth signals, including cell proliferation, tumor invasion, and autophagy, and prevents apoptosis." (PMID 30769863, 2019). "Hypoxia, and the nutrient deficit produced in the TME due to rapidly growing tumor cells, leads to inhibition of the mTOR pathway in T cells, resulting in inefficient proliferation, and reduced effector function and differentiation into Treg." (PMID 31468283, 2019).
tumor (continued). "Sirolimus analogs (rapalogs and mTOR inhibitors), such as everolimus, temsirolimus, and ridaforolimus, not only improved radiotherapy efficiency but also reduced tumor recurrence." (PMID 31929797, 2019). "In TSC, mutation of TSC1 or TSC2 leads to a disinhibition or hyperactivation of the mTOR pathway, which promotes increased cell growth and proliferation and tumor formation." (PMID 31838997, 2019). "Compared with placebo, mTOR inhibitors significantly reduced tumor volume in both AML (RR = 24.69, 95% CI = 3.51,173.41, P = 0.001) and SEGA (RR = 27.85, 95% CI = 1.74,444.82, P = 0.02)." (PMID 30760308, 2019). "The increased mTORC1 activity due to EZH2 mutant repression of Sestrin1, which acts as a tumor suppressor, likely contributed to the sensitivity of these tumors to mTOR inhibition." (PMID 31817676, 2019). "In colorectal cancer, 40%-60% of tumours show mTOR activation and everolimus showed some efficacy in patients with metastatic colorectal cancer in Phase I studies." (PMID 35582282, 2019). "Using the same mechanism to activate PI3K/AKT/mTOR pathway has presented enhanced tumor progression and poor survival response to patients with different types of tumors." (PMID 31075885, 2019). "This study indicated that mTOR inhibition alleviates tumour burden, although further molecular analysis is required to identify predictive parameters for temsirolimus guided treatment response." (PMID 30970654, 2019). "The obtained results showed that everolimus and metformin cooperate to inhibit mTOR activity, tumor cell growth and colony formation, independently of glucose and O2 concentrations." (PMID 31921637, 2019). "A deeper understanding of the regulatory networks and the major alterations of PTEN expression and its related PI3K/AKT/mTOR pathway opens new insights for pharmacological targets and prognostic tumor biomarkers." (PMID 31366089, 2019). "Because mTOR is connected to networks formed by various signaling pathways in the cell survival process, mTOR signaling is important in tumor studies." (PMID 31929797, 2019). "The progesterone-treated group showed significantly lower expression of Akt, phospho-Akt, mTOR and phospho-mTOR in tumor tissue compared to vehicle controls." (PMID 30700763, 2019). "Taken together, these data documented that ALM enhances the anti-tumor effect of mTOR inhibitors both in vitro and in vivo, suggesting its therapeutic potential in combination therapy." (PMID 31083403, 2019). "Inactivation of the NF1 tumor suppressor in MPNST results in upregulation of mTOR (mammalian target of rapamycin) signaling and angiogenesis, which contributes to disease progression." (PMID 31427883, 2019). "In a recent study, Salmonella downregulated IDO expression in B16F10 and 4T1 tumor cells via inhibition of AKT /mTOR/p70S6K signaling pathway, and thus resulted in a decrease in kynurenine concentration." (PMID 31052558, 2019). "Patients with increased p-mTOR expression in tumoral tissue showed higher tumour recurrence rates during follow-up (23.8% vs. 5.9% at 24 months; log rank p = 0.04)." (PMID 30650598, 2019). "To explore the molecular mechanisms of LHX2 during tumor progression, we assessed several critical regulators of the Akt/mTOR pathway." (PMID 31724536, 2019). "Several studies have also shown the importance of mammalian target of Rapamycin (mTOR) activation in HB tumor growth." (PMID 30863496, 2019). "The PI3K/AKT/mTOR pathway plays a critical role in the proliferation, apoptosis, angiogenesis, and metastasis of tumor development." (PMID 31191795, 2019). "In the present study, we investigated the anti-neoplastic effects of casticin (CTC), identified from the plant Vitex rotundifolia L., alone and/or in combination with BEZ-235, a dual Akt/mTOR inhibitor in human tumor cells." (PMID 30813295, 2019).